KEAP1 (kelch like ECH associated protein 1)
Diseases named in the same sentence as KEAP1 in open-access papers (continued):
Sharing a sentence is not in itself a finding about the gene and the disease.
liver fibrosis (continued). "Background and Aim: To investigate whether double-knockdown of PHD1 and Keap1 in mice could enhance the resolution of carbon tetrachloride (CCl4)-induced liver fibrosis." (PMID 29899699, 2018). "It was discussed whether the mechanism of YJSB against liver fibrosis was by regulating proteins in the Keap1-Nrf2 pathway, enhancing the protective effect on liver cells, reducing the production of oxidative stress factors, and thereby inhibiting the process of liver fibrosis." (PMID 37229248, 2023). "According to an earlier study, activation of the Keap1-Nrf2 pathway could inhibit the activation of hepatic stellate cells and their production of a large amount of collagen, thus, inhibiting the occurrence and development of liver fibrosis." (PMID 37229248, 2023). "This review describes Kelch-like epichlorohydrin-associated protein 1 (KEAP1)/NRF2 signaling mechanisms and presents recent research advances regarding NRF2 and its involvement in primary fibrotic lesions such as pulmonary fibrosis, hepatic fibrosis, myocardial fibrosis, and renal fibrosis." (PMID 35721561, 2022). "The loss of PHD1, plus the downregulation of Keap1 (Kelch-like ECH-associated protein 1), a sensor of oxidative stress, favors the constitutive activation of HIF1-α, protecting hepatocytes against ischemia/reperfusion-induced liver injury and preventing liver fibrosis." (PMID 32764403, 2020). "Thus, Keap1 may be an efficient therapeutic target for relieving oxidative stress injury during liver fibrosis." (PMID 28539891, 2017). "PLS-PM results indicated that Tau positively affected the Nrf2/Keap1 pathway and negatively modulated the TLR4/NF-κB pathway, thereby improving intestinal barrier function and alleviating liver fibrosis." (PMID 40826133, 2025). "Five patients had liver diseases (polycystic liver disease, liver fibrosis, liver cirrhosis, or chronic hepatitis B) with an average of 97 small somatic variants, including nonsilent variants in ARID1A, CSMD3, and KEAP1 and one copy gain of PBX1." (PMID 38877653, 2024). "Our results showed that TP supplementation alleviated liver morphology, liver function and liver fibrosis; improved oxidative stress parameters; and increased the expression of STAT5b, Nrf2, HO-1 and NQO-1 and decreased the expression of Keap1 in the liver tissues of aged rats." (PMID 31819135, 2019). "FAN administration alleviated the inhibition of the Nrf2 pathway in the liver specimens of rodents with hepatic fibrosis by increasing the Nrf2 expression and its downstream detoxification enzymes’ (HO-1, SOD1, and CAT) protein levels and decreasing the protein level of Keap1." (PMID 40910002, 2025). "Finally, in the CCL4-induced rat hepatic fibrosis model, the YJSB drug group activated the Keap1-Nrf2 signaling pathway, resulting in Keap1 release in the cytoplasm and Nrf2 entry into the nucleus to initiate a series of antioxidant reactions and promote the generation of antioxidant proteins." (PMID 37229248, 2023). "As liver fibrosis is a complex process involving different types of cells, cytokines and signaling pathways, and it may also cross react with other genes while interfering with PHD1 and Keap1 genes." (PMID 29899699, 2018).
Hepatic steatosis (17 papers, 2013 to 2026). Steatosis is a term used to denote lipid accumulation within hepatocytes. "In leptin-deficient mice, constitutive activation of NRF2 via KEAP1-KD established insulin resistance, inhibited the accumulation of lipids in adipose tissue, and subsequently increased hepatic steatosis." (PMID 32751080, 2020). "Enhanced Nrf2 activation (via Keap1-KD) attenuated methionine- and choline-deficient diet-induced fatty liver by increasing hepatic antioxidant and detoxification capacity." (PMID 24224011, 2013). "Significant increases in muscle mass (quadriceps and gastrocnemius) were observed in Keap1-KO mice fed a western diet vs. obese fl/fl littermates, with coincident reduction in hepatic steatosis in KO animals." (PMID 33298924, 2020). "The current study demonstrated that increased Nrf2 activity in Keap1-KD mice decreased lipogenic gene expression of Fas, Acc1, and Scd1, which contributed to the decreased fasting-induced hepatic steatosis and lipid accumulation." (PMID 24224011, 2013). "Overall, the current study reports enhanced Nrf2 activity, genetically via Keap1-KD, prevented fasting-induced fatty liver by inhibiting fatty acid transport and impairing activation of the Pparα signaling pathway in liver." (PMID 24224011, 2013). "Genetically-enhanced Nrf2 activity by Keap1-KD prevented fasting-induced hepatic steatosis in mouse liver." (PMID 24224011, 2013). "Nrf2-null mice exhibited more severe hepatic steatosis, while Keap1-KD mice exhibited less, along with decreased CD36 and Fgf21 expression, suggesting Nrf2 negatively regulate lipogenesis and hepatic lipid accumulation." (PMID 24224011, 2013). "Moreover, constitutive activation of Nrf2 induced by Keap1 gene knockdown promoted high fat diet (HFD)-induced fatty liver and glucose intolerance in Leptin-null (Lepob/ob) mice." (PMID 29241092, 2018). "The pathogenic mechanism was elucidated by demonstrating, for the first time, that VPA binds to KEAP1, causing NRF2 to migrate to the nucleus and subsequently activate the transcription of FATP2, ultimately increasing fatty acid uptake, which triggers hepatic steatosis." (PMID 40303331, 2025). "Of note, it has also been reported that the activation of the Keap1/Nrf2 signaling pathway to maintain a redox status mediates lipid metabolism-related genes (SREBP-1c and PPARα) to reduce hepatic steatosis in an HFD-induced obese animal model." (PMID 36358563, 2022). "Furthermore, constitutively activated NRF2 signaling in Keap1-KD mice fed a HFD exhibited greater lipogenic gene expression, inflammation, and increased hepatic steatosis." (PMID 32751080, 2020).
osteoporosis (17 papers, 2022 to 2025). A condition of reduced bone mass, with decreased cortical thickness and a decrease in the number and size of the trabeculae of cancellous bone (but normal chemical composition), resulting in increased fracture incidence. "The NRF2/KEAP1 pathway has been found to mitigate bone loss, decrease fracture risk and reduce the incidence of osteoporosis." (PMID 35955599, 2022). "In the glucocorticoid-induced osteoporosis rat model, the use of Gastrodin was found to improve osteoporosis status by activating the Nrf2/Keap1 pathway and upregulating the expression of OCN, BMP-2, and RUNX2." (PMID 41282615, 2025). "Among absorbable components in AA, mangiferin has acted as a ferroptosis inhibitor through the Keap1/Nrf2/SLC7A11/GPX4 pathway in osteoporosis mice." (PMID 39512823, 2024). "Recent studies have reported that plant phenolic compounds such as 4-methylcatechol, oroxylin A, notopterol, and tussilagone have inhibitory effects on osteoporosis by acting on the Nrf2/Keap1 signaling axis and reducing oxidative stress levels." (PMID 39765903, 2024). "This cascade culminates in disrupted bone remodelling and exacerbated osteoporosis; conversely, activation of Nrf2/Keap1 signalling preserves cellular redox homeostasis, impeding the cytotoxicity effects induced by high glucose in osteoblasts." (PMID 37621124, 2023). "Overall, these findings suggest that AR/PCC herb pair can inhibit osteoblast pyroptosis and ameliorate the progression of osteoporosis in the vertebral bodies of DM rats by activating the Nrf2/Keap1 signalling pathway." (PMID 37621124, 2023). "Thus, OG prevented senile osteoporosis through attenuating oxidative stress and autophagy of osteoclast via activating Nrf2/Keap1 and mTOR signaling pathway." (PMID 35585885, 2022). "Indeed, NRF2/Kelch-like ECH-associated protein 1 (KEAP1) pathway, which scavenges ROS, promotes NF-κB and NFTAc1 and regulates osteoclastogenesis in vitro and in vivo, suggesting that NRF2 activators as a new therapeutic target of osteoporosis." (PMID 38040717, 2023). "Therefore, to contribute to the discovery of novel anti-osteoporosis agents, we identified KCB-F06 as a novel Keap1–Nrf2 PPI inhibitor that showed anti-osteoclastogenic activity in vitro and blocked OVX-mouse bone loss in vivo." (PMID 39061918, 2024). "Hence, we tried to find a novel and effective Keap1-Nrf2 PPI inhibitor and further evaluate its anti-osteoporosis activity to discover a novel anti-osteoclast drug candidate." (PMID 39061918, 2024).
Cerebral ischemia (15 papers, 2019 to 2025). Restriction of arterial blood supply to the brain associated with insufficient oxygenation to support the metabolic requirements of the tissue. "Similar studies have demonstrated that butyrate blocks liver injury and cerebral ischemia injury caused by various factors by regulating the Keap1/Nrf2 pathway." (PMID 38521894, 2024). "Oxidative stress caused by cerebral ischemia or intracerebral hemorrhage affects the conformation of Keap1." (PMID 35462700, 2022). "A Western blot analysis demonstrated the upregulation of nuclear factor erythroid 2–related factor 2 (Nrf2), heme oxygenase-1 (HO-1), and NAD(P)H:quinone oxidoreductase 1 (NQO1) and the downregulation of Kelch-like, ECH-associated protein 1 (Keap1) in the cerebral ischemia–reperfusion model." (PMID 40283984, 2025). "Recent studies demonstrated that NLRP3 inflammasome deficiency reduces cerebral ischemia-reperfusion injury by inhibiting ferroptosis, which may be achieved through the mechanism of the Keap1-Nrf2 pathway." (PMID 36818726, 2022). "Tetrahydrocurcumin (THC) inhibits ferroptosis and restores blood–brain barrier (BBB) function by activating the Keap1/Nrf2 signaling pathway, thereby alleviating neurological dysfunction induced by cerebral ischemia–reperfusion." (PMID 41273058, 2025). "The Keap1-Nrf2/HO-1 signaling cascade is regarded as the “switch” of the endogenous antioxidant system and can effectively mitigate damage from cerebral ischemia." (PMID 38664646, 2024). "This study has, for the first time, shown that APHD can significantly inhibit oxidative stress via the Keap1-Nrf2/HO-1 pathway and is expected to become a potential therapeutic against cerebral ischemia." (PMID 38664646, 2024). "A study has shown that Britanin leading to the induction of the Nrf2 pathway ameliorated cerebral ischemia–reperfusion injury by selectively binding to cysteine 151 of Keap1 and inhibiting Keap1-mediated ubiquitylation of Nrf2." (PMID 35462700, 2022). "A luciferase mouse model, a Keap1-dependent oxidative stress detector, was employed to visualize the time-dependent Nrf2 expression from brain ischemia onset through 7 days after tMCAO." (PMID 30890934, 2019). "Moreover, miR-34b was reported to participate in protecting against cerebral ischemia/reperfusion injury in rats via targeting Keap1 signaling pathway." (PMID 33724167, 2021). "The herb-derived compound, Britanin, selectively binds to a conserved cysteine residue, cysteine 151, of Keap1 and reduces Keap1-mediated ubiquitination of Nrf2, which results in activation of the Nrf2 pathway and attenuating cerebral ischemia-reperfusion-induced damage." (PMID 32089771, 2020). "THC inhibits ferroptosis through the activation of the Keap1/Nrf2 signaling pathway, significantly improving BBB dysfunction and alleviating neurological deficits following cerebral ischemia–reperfusion." (PMID 41273058, 2025). "The findings reveal for the first time that THC inhibits ferroptosis through the activation of the Keap1/Nrf2 signaling pathway, significantly improving BBB dysfunction and alleviating neurological deficits following cerebral ischemia–reperfusion." (PMID 41273058, 2025). "For instance, it inhibited β-amyloid-induced neuroinflammation via the Nrf2/Keap1 pathway, alleviated high glucose-induced renal mesangial cell injury through the ROS/Nox4/ERK1/2 axis, and reduced cerebral ischemia-reperfusion injury by promoting neuronal survival and suppressing neuroinflammation." (PMID 41573542, 2025). "The detailed mechanism of the protective effects of simple O-substituted isoflavones against cerebral ischemia reperfusion might be related to the PI3K/AKT/ERK/mTOR or GSK-3β pathway, eNOS/Keap1/Nrf-2/HO-1 pathway, TLRs/TIRAP/MyD88/NFκ-B pathway, and Bcl-2-regulated anti-apoptotic pathway." (PMID 36142301, 2022).
liver disease (15 papers, 2020 to 2025). "The incorporation of KEAP1 into p62 bodies requires phosphorylation of p62 at serine 349, implying that kinase activation or phosphatase inhibition in liver disorders may be linked to pathogenesis." (PMID 40437287, 2025). "Structures known as Mallory-Denk bodies, which are positive for p62, KEAP1, and ubiquitin, have been observed in various liver disorders, including NASH and HCC." (PMID 40437287, 2025). "Recent mechanistic studies have shown that ELANE promotes KEAP1 protein stability, inhibiting NRF2‐mediated ferroptosis in metabolic dysfunction–associated steatotic liver disease." (PMID 40895144, 2025). "Although p62 bodies containing KEAP1 are degraded by autophagy, they accumulate in various liver disorders." (PMID 40437287, 2025). "Keap-1/Nrf2 is the major antioxidant-signaling pathway that stimulates antioxidant expression and plays a significant role in protecting against various liver disorders and preventing NAFLD." (PMID 38231665, 2023). "miR-200a inhibits oxidative stress and inflammatory response by suppressing Keap1 and activating the Nrf2 pathway in the development of liver disease." (PMID 36158873, 2022). "Given the genetic analyses in mice in this study, it is conceivable that blocking KEAP1 incorporation into p62 bodies in human liver diseases could serve as a therapeutic target." (PMID 40437287, 2025). "In addition to experimental models, several lines of evidence suggest the clinical relevance of p62 body formation and KEAP1 sequestration in human liver diseases." (PMID 40437287, 2025). "The aim of this review is to provide an up-to-date overview of the Keap1/Nrf2 signaling pathway and its involvement in the development of main liver diseases such as alcoholic liver damage, viral liver diseases, steatosis, steatohepatitis, cholestatic damage, and liver cancer." (PMID 33066023, 2020). "Moreover, the activation of the Keap1-Nrf2 pathway may offer protective effects against hepatotoxicity, with potential implications for human liver disease." (PMID 39771079, 2024). "Further investigations using additional in vivo liver disease models—such as NASH and HCC—will be important for defining the broader role of autophagy suppression and KEAP1-p62 interaction in disease progression." (PMID 40437287, 2025). "The Keap1-Nrf2-ARE pathway is closely related to diseases such as central nervous system disease, cardiovascular system disease, liver disease, lung disease, kidney disease, tumors, etc.." (PMID 36408214, 2022).
bladder cancer (14 papers, 2019 to 2024). "The p62/Keap1/nuclear factor erythroid 2-related factor 2 (NRF2) pathway exerts oncogenic effects in bladder cancer." (PMID 38027016, 2023). "In circumstances of impaired autophagy, for instance, the accumulation of p62 promotes bladder cancer cell proliferation via sequestrating KEAP1 to upregulate antioxidant genes and protect cancer cells from oxidative stress." (PMID 34575683, 2021). "Meanwhile, the PTMA interacts with TRIM21 directly to regulate the Nrf2 expression through p62/Keap1 signaling in human bladder cancer." (PMID 30988666, 2019). "NEDD4L inhibits bladder cancer progression by inactivating the p62/Keap1/Nrf2 pathway." (PMID 38526036, 2024). "NEDD4L also inactivates the p62/Keap1/Nrf2 pathway to promote bladder cancer cell apoptosis." (PMID 38027016, 2023). "In addition, NEDD4L inhibits cisplatin resistance in bladder cancer cells by inactivating the p62/Keap1/Nrf2 pathway." (PMID 38027016, 2023). "After receiving THP treatment, the bladder cancer cell lines could upregulate the expression of the AKR1C1 gene through the ROS/KEAP1/NRF2 pathway, leading to resistance to THP treatment." (PMID 37173953, 2023). "Additionally, NEDD4L inactivates the p62/Keap1/Nrf2 pathway, inhibiting bladder cancer cell migration and invasion." (PMID 38027016, 2023). "The expression levels of p62, p-Nrf2 and NQO1 was upregulated and reached its peak level at 12 h in C-2-treated bladder cancer cells, and the expression of Nrf2 and Keap1 has no obviously changes." (PMID 31685029, 2019). "Destruction of the crosstalk between p62 and Keap1-Nrf2 pathway through inhibiting the initiation of JNK-mediated autophagy by SP600125 triggering the switch from autophagy to apoptosis, which could be utilized for sensitizing bladder cancer cells to treatment with C-2." (PMID 31685029, 2019).